SLC9B1P1 (solute carrier family 9 member B1 pseudogene 1)
Synonyms: NHEDC1P1
Gene: Unprocessed pseudogene on chromosome Y (11,340,579 to 11,385,687, reverse strand). Ensembl gene ENSG00000183704.
Subcellular location: Membrane